SDC1 (syndecan 1)
Diseases named in the same sentence as SDC1 in open-access papers (continued):
Sharing a sentence is not in itself a finding about the gene and the disease.
tumor (continued). "Although there are conflicting reportsof a role for syndecan-1 in cancer, the importance of these studies is theidentification of a PPARγ molecular target that is regulated byPUFAs and results in functional response in the tumor cells." (PMID 18769551, 2008). "In summary, the loss of syndecan-1 by carcinoma cells leads to the appearance of a more aggressive phenotype and behaviour of carcinoma cells, whereas the expression of syndecan-1 in the reactive stromal cells creates a favourable microenvironment for tumour cell growth and angiogenesis." (PMID 18542065, 2008). "Reduced tumor syndecan-1 staining also correlated with upregulation of stromal fascin (p = 0.016)." (PMID 18590537, 2008). "However, reduced tumor cell staining for syndecan-1 correlated significantly with strong stromal staining for fascin (p = 0.016)." (PMID 18590537, 2008). "The TMA cores included the tumor borders, however we did not detect any consistent specific association of syndecan-1 immunoreactivity with tumor edges." (PMID 18590537, 2008). "It is likely that stromal syndecan-1 has impact on the tumor microenvironment by alterations to the retention of heparin binding growth factors and extracellular matrix components in the vicinity of the tumor." (PMID 18590537, 2008). "Sdc1-integrin complexes may thus synergistically contribute to tumour progression driven by c-met overexpression." (PMID 17244359, 2007). "In DCIS, coexpression of ET receptors, E-cad, c-met and Sdc1 may constitute a specific expression signature indicative of the transition of an early stage to later stages of tumour progression." (PMID 17244359, 2007). "Tumour cells exhibited variable expression of Sdc1, ranging from weak to strong." (PMID 17244359, 2007). "In the present study we evaluated coexpression of the three functionally linked prognostic factors, namely Sdc1, E-cad and c-met, in ductal carcinoma in situ (DCIS) of the breast by semiquantitative immunohistochemistry of a tissue microarray containing tumour specimens from 200 patients." (PMID 17244359, 2007). "In a univariate analysis, syndecan-1-positive tumours were associated with higher overall (P = 0.001) and recurrence-free survival (P = 0.003) than those tumours with no or little syndecan-1 expression." (PMID 8054282, 1994). "Consequently, we hypothesize that SDC1 may function as a pivotal gene influencing the proliferation and progression of fibroblasts, macrophages, and cancer cells within the tumor microenvironment of TNBC." (PMID 41209699, 2025). "Moreover, a marked positive correlation was detected between SDC1 expression and cellular senescence in TME, suggesting that SDC1 may serve as a potential tumor senescence-related marker." (PMID 41209699, 2025). "Furthermore, cellular communication and GO enrichment analyses indicated that SDC1 may play a role in the establishment of a tumor-promoting microenvironment through an exosome-mediated paracrine mechanism." (PMID 41209699, 2025). "Finally, using in vitro experiments, we verified that the target protein SDC1 in tumor cells is influenced by C0 MYH11 + fibroblasts and may play an active role in inhibiting CC progression and immunosuppression." (PMID 40616092, 2025). "However, the superior sensitivity and yield of serum MMP‐7 levels over SDC1 in PDAC, suggests that it may be the dominant modulator in tumor progression and microenvironment, possibly thorough several mechanisms of which one is the release of SDC1 ectodomain." (PMID 39263943, 2024). "Additionally, SDC1 was also closely related with TILs in tumor cells and CAFs and may be involved in the regulation of TILs by various means." (PMID 37069585, 2023). "Finally, performing an in silico analysis with public databases from TCGA and GEO (cohorts GSE9891, GSE3149, GSE26193, and GSE63885), the authors found that syndecan-1 expression level negatively correlated with OS in OC patients and that syndecan-4 expression increased across tumor stage." (PMID 37370735, 2023).
tumor (continued). "Additionally, IF results showed the SDC1, as well as M2 macrophage biomarker CD206, were both of higher abundance in BC samples of high-risk patients, suggesting that SDC1 was indeed a tumor-promoting factor as previously reported and was positively linked to the expression of M2 macrophages." (PMID 35793235, 2022). "However, it remains unclear if SDC1 shedding probably involved in paracrine communication within the tumor microenvironment may also lead to quantifiable concentrations of the free SDC1 ectodomain in blood." (PMID 36353562, 2022). "Furthermore, tumor cell growth can be aided by SDC1-positive fibroblasts in vitro." (PMID 36591476, 2022). "Consequently, cancer cell pathophysiology including tumor growth, metastasis and angiogenesis is uniquely affected by whether SDC-1 is membrane-bound, shed or transported to the cell nucleus." (PMID 35118073, 2021). "Finally, syndecan-1 immunostainings of primary tumors and livers from control and tumor-bearing mice indicate that this proteoglycan may be involved in Mn distribution in vitro, as well as in vivo." (PMID 34349175, 2021). "Additionally, it has been shown that HPSE enhances the shedding of syndecan-1 from tumor cells." (PMID 34578329, 2021). "Although data detailing the relationship between tumor progression and changes in the location of SDC-1 expression are scarce, analysis of available literature would nevertheless further understanding of molecular events associated with variations in SDC-1 localization." (PMID 35118073, 2021). "In addition, high SDC1 mRNA levels in whole tissue lysates may originate from tumor-infiltrating plasma cells and not only carcinoma cells." (PMID 34206469, 2021). "In addition, the cleavage of SDC1 by MMPs is involved in tumor invasion and proliferation." (PMID 34113616, 2021). "Based on these observations, the shedding of SDC1 from the tumor cell surface, and consequently its appearance in the tumor stroma, may be associated with tumor aggressiveness, invasion, and progression but, in the meantime, it does not seem to be predictive for platinum-based chemotherapy." (PMID 33114033, 2020). "However, a significant reduction of cell surface tethered SDC1 and an increase of shed SDC1 in the ECM has been observed as a function of tumor progression and aggressiveness, suggesting the involvement of post-transcriptional mechanisms in SDC1 expression in this type of tumor." (PMID 32916872, 2020). "Collectively, these data highlight a fundamental functional relationship between Sdc1 expression and bcCML migration and localization, and raise the exciting possibility that disabling Sdc1 function could be implemented as a strategy to reduce tumor burden, as well as systemic dissemination." (PMID 33243988, 2020). "The presence of heparanase in the nucleus leads to loss of the heparan sulfate proteoglycan syndecan-1 from the nucleus, resulting in enhanced histone acetyltransferase (HAT) activity and upregulation of expression of VEGF and MMP9, two genes that contribute to an aggressive tumor phenotype." (PMID 32899927, 2020). "SDC1 tumor immunoexpression may be increased or decreased in epithelial malignant neoplasms compared to that in adjacent non-neoplastic tissue, depending on the type of carcinoma, and it has been correlated with various clinicopathological parameters and patient prognosis." (PMID 31182980, 2019). "The combined results explained the influence of the tumor microenvironment in carcinogenesis, which led to insight into the possible molecules, such as syndecan-1 and heparanase, which could be used as targets for tumor prognosis and as future supplementary treatment for cancer." (PMID 30922347, 2019). "Similarly, we could observe that tumor cells more prone to metastasize, such as 4T1-shRNA-Gal-3 cells, presented decreased levels of Sdc1." (PMID 31949431, 2019). "Any role of endothelial Sdc1 in tumor cell extravasation is speculative at this point." (PMID 29976229, 2018).
tumor (continued). "The aim of our study was to determine and compare the Sdc1 expression in the malignant epithelial cells and stroma of 30 ILCs and 30 IDCs, as well as in the axillary lymph node metastases of ductal type, and to correlate it with the clinical and tumor parameters." (PMID 30151336, 2018). "Loss of nuclear syndecan-1 was shown to be induced by elevated levels of heparanase, which resulted in a significant increase in histone acetylase activity, leading, in turn, to stimulation of the transcription of genes (i.e., VEGF and MMP-9) that drive aggressive tumor behavior." (PMID 30413079, 2018). "Therefore, we examined whether host Sdc1 affects these cellular constituents of the local tumor microenvironment." (PMID 29976229, 2018). "However, in different types of cancers, syndecan-1 and syndecan-4 may present the opposite effect, promoting the tumor progression." (PMID 30027065, 2018). "In addition, heparanase and syndecan-1 may cooperate to drive growth factor signaling and to regulate cell behavior, thus enhancing tumor growth and dissemination." (PMID 26869927, 2016). "Thus, a significant inverse correlation was demonstrated between S1P1 and syndecan-1 in HCC tumor." (PMID 27556509, 2016). "The reason for this could be that a part of soluble syndecan-1 originates from the tumor tissue." (PMID 26420915, 2015). "Accumulating evidences suggest that the localization of syndecan-1 might be crucial for its function and the nuclear translocation adds additional complexity which needs to be further addressed in the context of variously differentiated tumor components." (PMID 24392351, 2013). "Furthermore, modulation of syndecan-1 affects the biological behavior of mesenchymal tumor cells and this involves genes regulating cell growth, cell cycle progression, adhesion, migration, and extracellular matrix organization; orchestrated in a complex network of signaling pathways." (PMID 24392351, 2013). "It will be worthwhile to explore whether Sdc1 is involved in gliomagenesis through facilitating the Wnt signaling pathway, as we have found for normal NPCs, as this could provide an extracellular target for combating tumor growth." (PMID 22936997, 2012). "However, juvenile Sdc-1 null mice have an increased resistance to tumor development." (PMID 22912899, 2012). "Furthermore, Sdc1 knockout mice and are resistant to Wnt1 induced tumor formation." (PMID 22936997, 2012). "We were the first to show that the RMKKK motif present at the juxtamembrane region of the cytoplasmic domain, may serve as a nuclear localization signal (NLS) guiding syndecan-1 to the nucleus and, in parallel, decreases the proliferation of two mesenchymal tumor cell lines." (PMID 21731601, 2011). "The resulting changes in gene expression facilitated by the loss of nuclear syndecan-1 could explain how heparanase enhances expression of MMP-9, VEGF, tissue factor and perhaps other effectors that condition the tumor microenvironment to promote an aggressive cancer phenotype." (PMID 19305494, 2009). "Thus there does not appear to be a close biological relationship between syndecan-1 status and microsatellite instability, which is strongly associated with tumor location in the proximal colon." (PMID 18590537, 2008). "From study of contiguous sections of the same Cleveland Clinic colorectal tissue microarray specimen set stained for syndecan-1, we identified that loss of tumor cell syndecan-1 did not correlate with the upregulation of fascin in clinically aggressive adenocarcinomas." (PMID 18590537, 2008). "these genes, Insulin Like Growth Factor 1 (IGF1) and Secreted Frizzled Related Protein 1 (SFRP1), were found to be down-regulated in tumor tissues, while the third gene, SDC1, also known as Syndecan 1, was found to be up-regulated in tumor tissues." (PMID 41209699, 2025).
tumor (continued). "NONO knockdown significantly downregulated the core clock gene PER2 and the oncogene DEC1 and markedly reduced tumor-cell expression of key fibroblast-signal receptors, including ITGB1, SDC1, and CD47." (PMID 41174721, 2025). "SDC1 (Syndecan-1) modulates cell adhesion and interaction with the extracellular matrix (ECM), impacting tumor progression and chemotherapy resistance." (PMID 40226632, 2025). "For instance, SDC1 overexpression in HCC suppresses autophagy via PI3K/AKT/mTOR activation, thereby enhancing tumor survival and metastatic potential." (PMID 41573680, 2025). "For cancer mortality, it identified proteins involved in tumour proliferation and microenvironment modulation (CEACAM5, KRT19 and SDC1), demonstrating COMET’s capacity to uncover meaningful molecular mechanisms." (PMID 40008295, 2025). "On the other hand, from methylation analysis, we observed that the promoter region of HGs such as KRT19, MMP1, COL11A1, SDC1, FN1, and COL5A1 is significantly methylated in normal tissue than in tumor tissue." (PMID 38639039, 2024). "This empirical verification affirms that both SDC1 and SDC4 play an integral role in promoting EMT in CRC cells, consequently propelling tumor progression and metastasis, a finding consistent with our earlier results derived from enrichment analysis." (PMID 38683136, 2024). "In a landmark study by Yao and colleagues, in transgenic mice models of PDAC, oncogenic KRAS induced SDC1 cell surface overexpression, where it regulated macropinocytosis, a crucial metabolic pathway that fuels PDAC cell growth and promotes tumor progression." (PMID 39263943, 2024). "In contrast, ERBB2, SDC1, and MMP14 exhibited elevated expression levels in the tumor group (All p < 0.05)." (PMID 38189813, 2024). "In this study, we noticed that the promoter regions of five HGs, such as KRT19, MMP1, COL11A1, SDC1, FN1, and COL5A1 were highly methylated in normal compared to tumor patients." (PMID 38639039, 2024). "Tumor cell clusters with diffused WGA staining exhibited cytoplasmic redistribution of E-cadherin, β-actin, syndecan-1, and morphological alterations from polygonal to elongated cells." (PMID 39830560, 2024). "Our data revealed that secretion of multiple ligands by macrophages, endothelial cells, and fibroblasts converge on the same receptors, such as SDC1 and SDC4 on tumor cells." (PMID 38546390, 2024). "Regression analysis of tumor tissue volume and expression of SDC1 and ITGA2 showed a positive correlation ed with the expression of SDC1 and ITGA2." (PMID 37907515, 2023). "To enhance our insights into the prognostic validity of the five-gene signature, we examined the expression of ATP6AP1, SLC7A5, EPDR1, SDC1, and PIGR in 13 paired BC samples, comparing them with their adjacent non-tumor tissues through RT-PCR." (PMID 38162504, 2023). "In the TNBC cohort, patients with high SDC1 expression in tumor cells and low expression in CAFs had significantly lower disease-free survival (DFS) and fewer tumor-infiltrating lymphocytes (TILs)." (PMID 37069585, 2023). "We found that the key genes, especially SDC1, SDC4, ITGA2, and ITGA3, in malignant cells that interacted with CAFs and Angiogenic_EC were positively correlated with the pEMT score in tumor cells." (PMID 38002057, 2023). "Systemic administration of synstatin retarded tumor growth in a xenografted mice model with MDA-MB-231 cells and corneal angiogenesis in vivo, reinforcing the role of SDC1 in regulating αvβ3- and αvβ5-induced tumorigenesis and angiogenesis." (PMID 36980680, 2023). "Considering the nature of syndecan-1, however, one must take into account that it can shed into the ECM, be reabsorbed by tumor cells or enter the nucleus." (PMID 38139365, 2023).
tumor (continued). "To investigate whether the pEMT biological process is potentially caused by SDC1, SDC4, ITGA2, and ITGA3 expressed by CAFs, we further focused on the correlation between the ligand genes from CAFs as well as from Angiogenic_EC with the abundance of malignant tumor cells undergoing pEMT." (PMID 38002057, 2023). "Meanwhile, the corresponding receptors (integrin αVβ8, syndecan 1 and 4, and CD44) are actively expressed in tumor cells." (PMID 37479733, 2023). "SDC1 and ADH1B were significantly expressed low in the normal tissues when compared to the tumor tissues, which were opposite at the protein level." (PMID 35280985, 2022). "As suggested from the existing studies, the high expression of SDC-1 can significantly promote the microvessel density in MPM tumors and promote tumor migration." (PMID 36523602, 2022). "We detected significant downregulation of IRS2 and NT5E in tumor tissues, whereas CACNA1H, CHPF, SDC1 and ATP6AP1 were highly expressed in tumor tissues than in normal tissues." (PMID 36277284, 2022). "The mRNA expression of SDC1 and ADH1B were significantly lower in the tumor tissues when compared to the normal tissues, which were opposite at the protein levels through the HPA database." (PMID 35280985, 2022). "Immunohistochemistry microarray was used to further confirm that protein expression of CD24, MMP1, SDC1, and SPP1 was much higher in tumor sections than in Para cancerous tissues." (PMID 35037689, 2022). "Synstatin, a mimetic peptide, inhibits the signaling complex formation between SDC-1, IGF1R, and integrin αvβ3 and attenuates HS-dependent angiogenic VEGF and FGF2 signaling, and blocks tumor angiogenesis in vivo." (PMID 36551220, 2022). "MMP1, SDC1, SPP1, and CD24 mRNA declaration was much higher in tumor tissues than in non-tumor tissue." (PMID 35037689, 2022). "Expectedly, HSPA4 overexpression increased the levels of HSPA4, HSPA5, CHOP, SDC-1, SDCBP-1, SOX4, FZD4, and β-catenin in tumor tissues, but 4-PBA inhibited the generation of these proteins." (PMID 35442158, 2022). "Considering that shed SDC-1 increases VCAM-1 expression, shed SDC-1 delivered from distant tumor microenvironments similarly promotes growth in otherwise dormant cancer cells and thus facilitates disease relapse and metastasis." (PMID 35118073, 2021). "Pre-analysis centrifugation of samples spiked with the T24 tumor cell line reduced levels of MMP9, SDC1, PAI1, ApoE, and ANG." (PMID 34204951, 2021). "In conclusion, we demonstrated that nuclear translocation contributes to the capacity of SDC1 to regulate EMT characteristics and the invasive behavior of tumor cells." (PMID 34208075, 2021). "Cell surface Sdc-1 on normal keratinocytes interacts with the LG4/LG5 domain of laminin-322, promoting cellular migration; similar interactions also operate in tumour cells." (PMID 33922532, 2021). "Sdc-1 can bind several growth factors, chemokines, cell adhesion molecules, and ECM components, allowing for the regulation of virtually all steps of tumor progression as defined in the Hallmarks of Cancer." (PMID 34070901, 2021). "The C2 cluster of cells were follicular B cells (MS4A1/CD20 and CD79A/B), which were found in lymphoid follicles of tertiary lymphatic structure within the tumor, and C0 and C4 clusters were antibody-secretory cells (MZB1 and SDC1/CD138)." (PMID 34367994, 2021). "In this study, we employed an in vivo-inspired 3D co-culture model of Sdc-1-depleted TNBC cells and HUVECs to study the impact of tumor cell Sdc-1 on angiogenesis in a defined setting." (PMID 34066023, 2021). "Syndecan-1 (SDC), a heparin sulfate proteoglycan, has been found to correlate with tumor progressions." (PMID 34600547, 2021). "The Sdc-1 ectodomain shed from the cell membrane by proteases can translocate to the nucleus of tumour cells and inhibit HAT and tumour development; however, this translocation process is blocked by HS." (PMID 33922532, 2021).